LMNB1 (lamin B1)
Diseases named in the same sentence as LMNB1 in open-access papers (continued):
Sharing a sentence is not in itself a finding about the gene and the disease.
cancer (continued). "Although this aspect does not appear to be directly germane to our study, ChIP-seq experiments could provide insight into the functional implication of lamin B1 loss on the 3D genome architecture of cancer cells." (PMID 27503568, 2016). "Every cancer cell line listed in the Human Protein Atlas has above-normal lamin B1 expression, (normal tissue indicated with black arrows, for LMNA the opposite holds true) (Human Protein Atlas." (PMID 39979866, 2025). "The present article systematically summarized and analyzed the recent progress in understanding the relationship between LMNB1 and cell senescence and malignant tumors." (PMID 38824174, 2024). "Another study reported that the inhibition of LMNB1 expression induced apoptosis by regulating cell cycle, cell migration, and cell proliferation in in vitro experiments and in mouse cancer models and weakened its invasive ability." (PMID 38824174, 2024). "Reduced LMNB1 gene expression was connected to a worse outcome, while greater LMNA gene expression has been associated with initial cancer stages." (PMID 38202898, 2023). "Among the 24 cancer types investigated, we found both B‐type lamins: lamin B1 and lamin B2 showed significant enrichment in tumor tissues (22/24 and 23/24 tumor types investigated, respectively), but LMNA was only enriched in 9/24 cancer types." (PMID 37218524, 2023). "The exposure of rat fibroblasts and human carcinoma cell lines to excessive ROS results in proteasome-mediated lamin B1 degradation." (PMID 37174634, 2023). "Lamin B1 was also oxidized and degraded in response to oxidative stress in a human carcinoma cell line." (PMID 37174634, 2023). "LMNB1 upregulation is generally observed in the tumor tissues of most TCGA cancer types, and is verified in kidney renal clear cell carcinoma using clinical specimens of our institute." (PMID 35241075, 2022). "The therapeutic effects of LMNB1 knockdown combined with PARP inhibition on human cancers were further investigated in vitro." (PMID 35241075, 2022). "Overexpression of LMNB1 generally predicted poor prognosis for cancer patients and suggested high level of CD4+ Th2 cell infiltration." (PMID 35241075, 2022). "The TIMER2.0 webserver was applied to study the differential expression of LMNB1 between tumor and adjacent normal tissues across 33 human cancer types in TCGA database." (PMID 35241075, 2022). "It remains to be elucidated how a majority of the cancers overexpressing lamin B1 manage to steer the DDR to specific NHEJ pathways." (PMID 36589746, 2022). "Through biometric analysis, we discovered that LMNB1 is substantially abundant in LUAD and is associated with cancer stage and patient prognosis in this study." (PMID 35712471, 2022). "It has been demonstrated that lamin B1 and lamin B2 are up- and down-regulated in several cancer cells and, accordingly, play different roles in cancer onset and development." (PMID 35132494, 2022). "Consistent with bioinformatics analysis, a moderate cohort of consecutive KIRC patients in our center also confirmed that LMNB1 was highly expressed in cancerous tissues and positively correlated with cancer aggressiveness." (PMID 35241075, 2022). "Herein, we aimed to provide a comprehensive research on the potential relationship between LMNB1 expression and immune infiltration levels across all TCGA cancers." (PMID 35241075, 2022). "The data on the transcription of LMNB1 mRNA in LUAD cancer cells and healthy cells was then obtained using bioinformatics approaches from the GTEx and TCGA databases." (PMID 35712471, 2022). "In conclusion, lamin B1 downregulation can be used reliably as a component of multiple biomarker batteries to identify therapy-induced senescence (TIS) in clinical cancer." (PMID 35328162, 2022). "In conclusion, our pan-cancer analysis provides a comprehensive overview of the oncogenic roles of LMNB1 in human cancers." (PMID 35241075, 2022).
cancer (continued). "In contrast, the infiltration level of CD4+ central memory T cells and CD4+ effector memory T cells was found negatively correlated high LMNB1 expression in more than half of the TCGA cancer kinds." (PMID 35241075, 2022). "Experiments have recently confirmed FOXM1's cell cycle regulation of LMNB1 and, thus, provide a mechanistic basis for a gene-gene scaling relationship between FOXM1 and LMNB1 across many cancers in TCGA." (PMID 35719698, 2022). "Enhanced migration rate is one of the cancer hallmarks, therefore, we compared lamin B1 and lamin A expression levels between normal cells and tumor cells as well as between primary tumors and their metastases using GTEx (for normal tissues) and TCGA datasets." (PMID 32987785, 2020). "LMNB1 and LMNB2 are coding genes for lamin B1 and lamin B2, respectively, which are nucleoskeleton components associated with cancer and aging." (PMID 32948197, 2020). "Lamin B1 RNA levels are significantly higher in various types of cancer including breast, kidney, liver, prostate, and skin." (PMID 32987785, 2020). "The important role of lamin B1 in cancer development and progression was further supported by cell culture studies and intravenous/subcutaneous injection of LLC1 and MLE12 cells." (PMID 31015297, 2019). "Grade I cancer cells expressed higher levels of nuclear lamin B1, both in terms of intensity and percentage of positive cells, whereas in grade II and especially in grade III tumors, much fewer cells expressed lamin B1, typically at substantially lower levels." (PMID 31015297, 2019). "This is due to the specific involvement of lamin B1 in carcinogenesis, since it increases in cancer cells more than cirrhotic cells." (PMID 30467522, 2018). "Depletion of lamin B1 in mouse embryonic stem or HeLa cells led to mitotic defects, such as delayed pro-metaphase as well as abnormal mitotic spindle assembly, these mitotic defects may ultimately lead to impaired chromosome segregation, which is one of the most important causes initiating cancer." (PMID 27449096, 2016). "In support for this, a recent study has shown that moderate reduction of lamin B1 in cancer cells delays cell cycle progression." (PMID 26469707, 2015). "Paired t-test revealed that there was significantly more lamin B1 staining in carcinomas relative to normal benign samples (2.7+/-0.03 vs. 1.7+/-0.03, p<0.001)." (PMID 26469707, 2015). "All the carcinoma samples were lamin B1 positive as well but 65% of the carcinomas showed high expression (grade 3) of lamin B1." (PMID 26469707, 2015). "LMNB1 has been upregulated in several cancers including cervical, liver, prostate, and esophageal." (PMID 40014866, 2025). "Targeting LMNB1 may provide therapeutic benefits by restoring the Th1/Th2 balance and improving patient outcomes, particularly in cancers with LMNB1 overexpression." (PMID 40315269, 2025). "Specifically, LMNB1 enhances cell proliferation, migration, and invasion, partly by disrupting interactions between the nuclear envelope and actin filaments, thereby facilitating cancer cell dissemination." (PMID 40315269, 2025). "This article focuses on the recent progress in understanding the role of LMNB1 in cell senescence and malignant tumors and offers insights that could contribute to elucidating the mechanism of action of LMNB1 to provide a new direction for further research." (PMID 38824174, 2024). "On the other hand, Lamin B1 upregulation is widely observed in tumor tissues of most cancer types." (PMID 38763973, 2024). "Therefore, further investigations on the relationship between LMNB1 and cell senescence and malignant tumors are required to derive concrete results." (PMID 38824174, 2024). "The present article reviews the current progress in the research on the relationship between LMNB1 and cell senescence and malignant tumors, with a hope to provide a reference for the diagnosis and treatment of diseases and to generate new ideas for further research." (PMID 38824174, 2024).
cancer (continued). "Moreover, the LMNB1 expression level was significantly correlated with prognosis in nearly 50% of the cancer cases studied." (PMID 38824174, 2024). "It is noteworthy that Lamin B1 expression level varies among different types of cancer tissue." (PMID 39727946, 2024). "Consequently, the ratios of lamin A/C relative to lamin B1 in the two cancer cell lines were substantially lower than in RPE-1 cells." (PMID 38228373, 2024). "The review found that LMNB1 played a certain role in the regulation of cell senescence process as well as in the early screening, diagnosis, and treatment and prognostic assessment of malignant tumors." (PMID 38824174, 2024). "The medication betulinic acid has anti-cancer properties in pancreatic cancer by limiting lamin B1 production, and it might be used as a biomarker for cancer." (PMID 38202898, 2023). "Previous studies have found that lamin B1 (LMNB1) contributes to the development of human cancers." (PMID 35436411, 2022). "Blockage of LMNB1 combined with PARP inhibitor treatment could be a promising therapeutic strategy for patients with cancers." (PMID 35241075, 2022). "Hence, this pan-cancer analysis was designed to investigate the precise role and possible mechanism of LMNB1 in all human cancer types." (PMID 35241075, 2022). "Firstly, Sangerbox tools helped us identified that activated CD4+ T cells and type 2 T helper cells were the main immune pathways which were significantly correlated with high expression of LMNB1 in most of human cancer types, especially ACC, KIRP, KIRC, LIHC, LGG, PRAD, THCA and UVM." (PMID 35241075, 2022). "Emerging evidence suggests that LMNB1 is involved in the development of multiple cancer types." (PMID 35241075, 2022). "The role of LMNB1 appears to be different in the various types of cancer." (PMID 36005596, 2022). "It has been reported that lack of lamin B1 in cancer cells causes chromosomal instability and persistent DNA damages." (PMID 35132494, 2022). "Furthermore, patients with high levels of FOXM1 and LMNB1 have poor survival, consistent with faster cancer growth." (PMID 35719698, 2022). "Additionally, TCGA data retrieved from GEPIA2 shows that most of the cancers show upregulated levels of lamin B1." (PMID 36589746, 2022). "However, it is noteworthy that should lamin B1 downregulation be used to identify senescence in clinical cancer samples, it must be combined with other senescence-associated biomarkers." (PMID 35328162, 2022). "More importantly, increased lamin B1 expression enhances cell migratory potential, and thus it might contribute to cancer progression and metastasis." (PMID 35328162, 2022). "Given that LMNB1 has different and complex biological functions in other tumor cells, in-depth research will lay a foundation for studying the pathological mechanisms of various diseases and exploring innovative biomarkers and targets for cancer therapy." (PMID 35712471, 2022). "Since LMNB1 is tightly correlated with HRR genes and plays an important role in DNA repair, we speculate that targeting LMNB1 could synergistically promote the effects of PARPi on cancer cells." (PMID 35241075, 2022). "LMNB1 is an important member of the lamin protein family but its role in cancer is controversial." (PMID 31105744, 2019). "We have previously shown that diamond, silica, and silver nanoparticles may promote a diminution in lamin B1 pools in different cell lines both normal and cancer cells that is a part of telomere-focused adaptive response." (PMID 26843106, 2017). "Taken together, these studies suggest that lamin B1 might be an important new target for anti-cancer therapies in a range of epithelial tumours." (PMID 24380701, 2014).
cancer (continued). "Hence, it is necessary to evaluate the expression level of LMNB1 in different malignant tumors." (PMID 38824174, 2024). "Thus, to a certain extent, LMNB1 is specifically expressed among various cancer types." (PMID 38824174, 2024). "Cell viability assay and western blotting experiment validate our thoughts, and these findings suggest that combination therapy of LMNB1 knockdown and PARPi could improve the prognosis of cancer patients without loss-of-function alteration of HRR genes." (PMID 35241075, 2022). "Since high expression of LMNB1 was found in the overwhelming majority of cancer types and correlated with cancer aggressiveness, we wonder whether it affects the prognosis of human cancers." (PMID 35241075, 2022). "Interestingly, the LMNB1 gene shows a significant number of deletions across cancers." (PMID 36589746, 2022). "Moreover, it has been demonstrated in cancer cells that a decrease of lamin B1 levels leads to a reduction of cell proliferation and deficiencies in DNA synthesis, resulting in the accumulation of cells in early S phase, probably due to a stalling of replication forks." (PMID 35132494, 2022). "Furthermore, lamin B1 associates G9a/GLP activity and H3K9me2/3 regions in large organised chromatin lysine modification blocks (LOCKs) during the processes of stem cell renewal, hematopoiesis and cancer progression." (PMID 26657637, 2016). "Oppositely, human cancer cell lines LNCaP, DU145, and HeLa retained similar levels of lamin B1 and emerin in the nuclear bleb compared to the body." (PMID 40060436, 2025). "By contrast, human cancer cell lines LNCaP, DU145 and HeLa cells retained similar levels of lamin B1 and emerin in the nuclear bleb compared to the body, suggesting that no rupture had occurred in those blebs." (PMID 41047936, 2025). "In various cancers, including HCC, LMNB1 is highly expressed and plays a significant role in promoting tumor progression." (PMID 40315269, 2025). "While LMNB1 protein levels were reduced, both senescent MCF7 and A549 cancer cells displayed increased nuclear staining for both LMNA and LMNB1." (PMID 41159617, 2025). "Recent studies have shown that oleuropein aglycone and hydroxytyrosol played a protective role in 8-Gy radiation-induced aging by maintaining LMNB1 expression and reducing the age-related SASP, which improved the efficacy and safety of cancer radiotherapy." (PMID 38824174, 2024). "LMNB1 is a biomarker of CD4+ Th2 cell infiltration and DNA homologous recombination repair in human cancers." (PMID 35241075, 2022). "Further investigation confirmed a strong positive relevance between LMNB1 expression and the 15 HRR genes in the PROfound trial in almost all TCGA cancer types." (PMID 35241075, 2022). "As shown in the pan-cancer view, the 4 hub genes (IFI16, LMNB1, RHBDF2, and TACC3) were significantly up-regulated in ccRCC samples and other cancer types when compared to adjacent normal tissues (p < 0.001)." (PMID 33796525, 2021). "Our functional experiments in cancer cell lines show that heterochromatin in cancer cells is tethered to the INM by LBR, which is downregulated together with lamin B1 at the onset of cell transition to senescence." (PMID 29415520, 2018). "Whereas TOM20 and Lamin B1 label all cell types, HER2 clearly marked the cancer epithelial cells in the breast tissue." (PMID 28098202, 2017). "As an experimental support, lamin B1 is shown to be depleted in senescent cells leading to chromatin reorganization in LAD and possibly linking to aging and cancer development." (PMID 26464434, 2016). "We identified a previously unrecognized feature of senescent cancer cells: an increase in LMNA and LMNB1 nuclear staining intensities despite reduced LMNB1 protein levels by immunoblot, which is in contrast to the typical reduction seen in primary senescent fibroblasts." (PMID 41159617, 2025).
cancer (continued). "A previous study showed that isolated micronuclei lacked functional LMNB1 and were more prone to envelope rupture, resulting in DNA damage, abnormal replication, and even cancer development." (PMID 38824174, 2024). "Lamin-A, C profiles appear strikingly similar to those for the mechanosensitive factors Vinculin, Yap1, and Piezo1, whereas datasets for lamin-B1 align with and predict regulation by the cell cycle transcription factor, FOXM1, and further predict poor survival across multiple cancers." (PMID 35719698, 2022). "Hence, once removed from cancer cells, IL6, IL8, VEGF, CDKN2A and LMNB1 mRNA levels in MSCs return to levels observed in MSCs without cancer cells." (PMID 36358839, 2022). "Indeed, the depletion of Lamin B1 in U2OS and HCT116 cancer cell lines leads to chromosomal instability and persistent DNA damages." (PMID 33918867, 2021). "Similarly to lamin B1, the role of PRC2 complex in cancer development is complex and cell-type specific." (PMID 31015297, 2019). "Specifically, we find that late replication timing is characterised by the presence of both lamin A/C and lamin B1 LADs rather than A/C or B1 alone, and LADs that are maintained between normal and cancer show consistent late replication timing." (PMID 30679435, 2019). "Normal gastric tissues showed the strongest lamin B1 positive staining, well-differentiated cases showed strongly positive lamin B1 expression, moderately-differentiated cases showed weakly positive expression, and the most poorly differentiated cancer samples show no detectable lamin B1 expression." (PMID 27449096, 2016). "Moreover, LMNB1 was universally correlated with HRR genes, which may serve as a potential therapeutic target to enhance the antitumor effect effects of PARPi in human cancers." (PMID 35241075, 2022). "However, there is no study reporting the potential role of LMNB1 in a systematic pan-cancer manner." (PMID 35241075, 2022). "The heatmap showed that LMNB1 expression had a strong positive correlation with the PROfound signature in the vast majority of TCGA cancer types, and the corresponding scatter plots of the cancer types whose Pearson correlation coefficient was not less than 0.80 were displayed." (PMID 35241075, 2022).